CFL1 (cofilin 1)
Diseases named in the same sentence as CFL1 in open-access papers (continued):
Sharing a sentence is not in itself a finding about the gene and the disease.
melanoma (continued). "We suggest that cofilin-1 could be included in a molecular profile signature for melanoma prognosis based on genes or proteins involved in control of invasion and metastasis." (PMID 29844875, 2018). "Thus, further in-depth investigations related to cofilin-1 pathway in melanoma would be relevant to define potential biomarker signatures for earlier prognosis and development of new targeted therapies." (PMID 29844875, 2018). "Thus, the mechanism by which cofilin-1 promotes amoeboid migration in monocytes is distinct from melanoma cells and may help monocytes avoid entrapment within the microvasculature." (PMID 38702365, 2024). "A similar study identified six more proteins overexpressed in melanoma cell lines compared to normal melanocytes, i.e., galectin-1, inosine-5′-monophosphate dehydrogenase 2, serine/threonine-protein phosphatase 2A 65 kDa regulatory subunit A α isoform, protein DJ-1, cyclophilin A and cofilin-1." (PMID 32331267, 2020). "Besides, a previous work from our laboratory demonstrated in a melanoma model with different degree of malignancy a correlation among the high levels of cofilin-1 and the migratory, invasive and metastatic ability of cells, suggesting its relevance in melanoma progression." (PMID 29844875, 2018). "Besides, proteomic studies showed differential expression of cofilin-1 isoforms in two melanoma cell lines compared with a melanocyte cell line and increased expression of cofilin-1 in metastatic lymph node compared with matched human primary cutaneous melanoma tissue of the same patients." (PMID 29844875, 2018). "Thus, more aggressive melanomas also exhibited increased nuclear levels of cofilin-1." (PMID 29844875, 2018). "In melanoma A375 cells, depleting both ADF and cofilin-1 had an additive effect on reducing the rate of bleb retraction, which points to these proteins having non-overlapping functions specifically at bleb necks." (PMID 34169836, 2021). "In melanoma A375 cells, a widely used cell line for the study of amoeboid migration, both ADF and cofilin-1 are expressed, with cofilin-1 mRNA levels being threefold higher." (PMID 34169836, 2021). "We report that melanoma cells depleted of cofilin-1 poorly undergo LBBM, whereas removing ADF did not have a significant effect." (PMID 34169836, 2021). "Thus, the dissemination of melanoma tumors is likely to be blocked by the simultaneous inhibition of ADF and cofilin-1." (PMID 34169836, 2021). "In melanoma cells, ADF appears to augment the activity of cofilin-1 at bleb necks." (PMID 34169836, 2021). "TCGA database analysis of melanoma also showed low survival in patients with upregulated cofilin-1 mRNA vs patients without alteration in CFL1 mRNA expression." (PMID 29844875, 2018). "This is in agreement with an in vitro previous study, where we reported high levels of cofilin-1 in migrating cells with metastatic ability compared with non-migratory neither metastatic control cells in an experimental model of human melanoma." (PMID 29844875, 2018). "Overall patient survival status analysis showed 59.3 % of deceased patients with melanomas where CFL1 expression was up-regulated vs 47 % of deceased patients with melanomas where CFL1 was no altered." (PMID 29844875, 2018). "A significant difference on the ratio of nuclear/cytoplasmic cofilin-1 mean fluorescence was found between these metastatic and non-metastatic melanoma cells." (PMID 29844875, 2018). "Finally, this work allowed proposing TYRP1, cofilin-1 and CAP1 as potential markers to detect melanomas with varying degrees of aggressiveness." (PMID 27206672, 2016). "However, the nuclear localization of cofilin-1 was not described in melanoma progression." (PMID 29844875, 2018). "Moreover, we found this effect to not be specific to melanoma A375 cells, as depleting lung adenocarcinoma A549 cells of both ADF and cofilin-1 similarly resulted in the elongation of bleb necks." (PMID 34169836, 2021).
glioma (7 papers, 2010 to 2023). A benign or malignant brain and spinal cord tumor that arises from glial cells (astrocytes, oligodendrocytes, ependymal cells). "Here we show that both The CFL1 and PGK1 expression can be used as prognosis factors for glioma patients, because both The CFL1 and PGK1 over-expression were associated with poor prognosis of radiotherapy cohort and entire followed-up cohort." (PMID 28903403, 2017). "The aim of the present study was to examine the potential association between CFL1 and radioresistance in human glioma cells." (PMID 25529407, 2015). "Recently, two lncRNAs have been identified as modulators of Cofilin-1 expression/function in different types of gliomas–Growth Arrest-Specific 5 (Gas5) and Aldoa repressor specify transcript (ARST)." (PMID 35447891, 2022). "By using 2D-HPLC-MS/MS method, we found that both PGK1 and CFL1 are abundantly expressed in the radioresistant glioma tissue from patients." (PMID 28903403, 2017). "Collectively our results indicate that over-expression of PGK1 and CFL1 can be closely related to glioma radiosensibility." (PMID 28903403, 2017). "In univariate and multivariate Cox regression, the results demonstrated The CFL1 (HR = 3.381, 95% CI = 2.020–5.659, p < 0.001) and PGK1 (HR = 2.509, 95% CI = 1.563–4.030, p < 0.001) over-expression were associated with the glioma progression." (PMID 28903403, 2017). "The multivariate Logistic regression demonstrated that the expression of CFL1 (p < 0.001) and PGK1 (p < 0.001) were associated with radioresistance in glioma." (PMID 28903403, 2017). "We also found that the over-expression of CFL1 or PGK1 can reduce glioma radiosensibility in vivo and in vitro, respectively." (PMID 28903403, 2017). "The over-expression of CFL1 and PGK1 were also associated with the poor prognosis of glioma patients." (PMID 28903403, 2017). "It was also reported that CFL1, as a downstream target of Rho-associated coiled-coil kinase (ROCK), plays a key role in glioma progression." (PMID 28903403, 2017). "The aim of the present study was to examine the association between cofilin-1 (CFL1) and radioresistance in human glioma U251 cells." (PMID 25529407, 2015). "The multivariate Cox regression in overall survival suggested that CFL1 level or PGK1 level could be the independent prognosis factor for poor prognosis in 113 glioma patients." (PMID 28903403, 2017). "A previous study reported that CFL1 was significantly upregulated in radioresistant astrocytomas; these findings suggested that CFL1 may be correlated with radiosensitivity in glioma." (PMID 25529407, 2015). "In addition, CFL1 expression was positively correlated with PGK1 expression in glioma." (PMID 28903403, 2017). "In addition, the regulator of cytoskeleton stability Cofilin-1 was also hyperphosphorylated at Ser3, indicating its inactivated state and therefore, potentially, a lesser contribution to the migratory phenotype of the glioma cells." (PMID 28978054, 2017). "CNTN1 was identified as a TAA along with other four TAAs (CRKII, CFL1, NME2, and TKT) in IDTH1-mutant lower grade gliomas through a proteomic and immunologic approach." (PMID 32752094, 2020). "In this clinical research, we further demonstrated that both CFL1 and PGK1 are also over-expressed in radioresistant glioma patients." (PMID 28903403, 2017). "In this study, both CFL1 and PGK1, as influential factors of radiosensibility, were expressed significantly higher in the radioresistant glioma patients." (PMID 28903403, 2017). "The univariate/multivariate Cox proportional hazards model revealed The CFL1 and PGK1 over-expression were the independent prognosis factors of glioma patients." (PMID 28903403, 2017). "The Kaplan-Meier survival analysis was used to describe the survival curves of the CFL1 and PGK1 over-expression groups and low-expression groups within each WHO grade II, WHO grade III and WHO grade IV gliomas." (PMID 28903403, 2017).
glioma (continued). "Additionally, it has been associated with high expression levels of Cofilin 1 and PGK1 with radioresistance in GBM patients, suggesting that Cofilin 1 and PGK1 can be used to evaluate glioma radiosensitivity and prognosis." (PMID 38139462, 2023). "Subsequently, the correlation of the expression of CFL1 and PGK1 with clinical characteristics was determined using the survival analysis in order to validate the prognosis of post-radiotherapy and overall glioma patients respectively." (PMID 28903403, 2017). "We previously reported that CFL1 and PGK1 are over-expressed in radioresistant U251 glioma cells." (PMID 28903403, 2017). "Thus, both CFL1 and PGK1 can be used as promising biomarkers for radiosensibility, prognosis and progression in glioma; and be potential therapeutic targets of glioma as well." (PMID 28903403, 2017). "In this study, the level of CFL1 and PGK1 of 113 glioma tissues were measured by ELISA method." (PMID 28903403, 2017). "The results suggested that as promising indicators, CFL1 and PGK1 could be used to evaluate glioma radiosensibility and prognosis." (PMID 28903403, 2017).
prostate carcinoma (7 papers, 2017 to 2025). A carcinoma that arises from epithelial cells of the prostate gland. "Noteworthy proteins upregulated in our dataset (case definition 1) and in the prostate cancer literature included cofilin 1 (CFL1) and Brefeldin-A-inhibited guanine nucleotide-exchange protein 1 (ARFGEF1)." (PMID 39125581, 2024). "For example, the effectiveness of docetaxel in prostate cancer cells was found to be greater when there is reduced expression of CFL1." (PMID 37371647, 2023). "It has reported that an increasing expression of Cofilin 1 is observed in 70% prostate cancers, and expression of Cofilin 1 is suggested as an independent predictive factor." (PMID 30858759, 2019). "In addition, cofilin-1 was identified as a novel mediator for the metastatic potentials and chemoresistance of prostate cancer cells." (PMID 36559193, 2022). "The following terms were combined in our search: prostate cancer; biomarkers; IL-17; STAT3; NRP1; LIMK1; Cofilin-1; PSMA; AMACR; CD15; Appl1; Sortilin; Syndecan-1, and p63." (PMID 37371647, 2023). "The percentages of alterations in these genes among prostate cancer varied from 13-30% for individual genes (CAP2, 19%; CAP1, 13%; CFL1, 30%; CFL2, 21%; DSTN, 19%); the CFL1 gene was amplified predominantly in the prostate cancer type." (PMID 28423713, 2017). "For example, percentages of alterations in CAP2, CAP1, CFL1, CFL2, DSTN, ACTB, and ACTG1 genes among prostate cancer varied from 2.6–30% in individual genes (CAP2, 19%; CAP1, 13%; CFL1, 30%; CFL2, 21%; DSTN, 19%; ACTG1, 2.6%; ACTB, 21%;); the CFL1 gene was amplified predominantly in prostate cancer." (PMID 28423713, 2017).
colon carcinoma (6 papers, 2015 to 2024). "In previous studies, elevated levels of CFL1 were correlated with an increased risk of lymph node metastasis and a deeper rate of local invasion in colon cancer." (PMID 39201394, 2024). "In colon cancer cells, CFL1 is mainly expressed on the cell edge, which is also the expression site of F-actin, indicating that CFL1 can cause stronger metastatic potential of tumor cells." (PMID 29347944, 2018). "Similarly, Cofilin 1, known to be involved in cytoskeletal remodeling, interacts with other proteins and is implicated in colon cancer cell migration." (PMID 35327385, 2022).
liver cancer (6 papers, 2009 to 2025). An epithelial or non-epithelial malignant neoplasm that arises from the liver. "Liao and colleagues reported that ERK phosphorylated CFL-1 conferred liver cancer cells with resistance to HDAC inhibitors." (PMID 31142371, 2019). "CAP2 was coexpressed with TP53BP2, ENA/VASP in the liver cancer, and CFL1, CFL2, DSTN, ACTB, ACTG1, and ROBO1." (PMID 28423713, 2017). "Another protein identified by us is cofilin-1 that was found to be down-regulated in liver cancer." (PMID 19737410, 2009).
lymph node metastasis (6 papers, 2018 to 2024). "However, CFL-1 levels association with dedifferentiation, infiltration depth, pathological staging, and presence of lymph node metastasis have also been found in other cancer types." (PMID 33482809, 2021). "In univariate analysis, parameters such as T grade (P = 0.011), lymphovascular invasion (P = 0.012), and high levels of CFL-1 and SSH1 (P = 0.0125) were significantly correlated with lymph node metastasis risk." (PMID 33482809, 2021). "The univariate analysis showed that a high concentration of sputum CFL1 is correlatedto T4 stage (P=0.01), presence of lymph node metastases (P=0.03), tobacco history(P=0.01), and squamous cell carcinoma subtype (P=0.04)." (PMID 29846436, 2018). "Furthermore, the increased expression of CFL1 was also observed in patients with lymph node metastasis (100 vs. 62.9%), although cofilin-1 status was independent of PSA level or age." (PMID 37371647, 2023). "The number of PFN1+ and CFL1+CD326+ CTCs was positively correlated with lymph node metastases." (PMID 37226274, 2022). "Kaplan-Meier survival analysis showed the degree of differentiation, tumor maximal diameter, TNM stage, lymph node metastasis, and surrounding invasion, and UGP2 and CFL1 expression were closely related to the average survival time of patients with PDC." (PMID 29347944, 2018). "To address whether CFL-1 and SSH1 protein levels could be prognostic factors for lymph node metastasis, we performed univariate and multivariate binary logistic regression analyses." (PMID 33482809, 2021).
ovarian carcinoma (6 papers, 2018 to 2025). A malignant neoplasm originating from the surface ovarian epithelium. "The association of cofilin-1 with the outcome of patients was also described in other types of tumors, i.e. lung, breast and ovarian carcinoma." (PMID 29844875, 2018). "Up-regulation of Cofilin-1 expression causes the progression of ovarian cancer." (PMID 31700829, 2019). "In ovarian cancer, miR-145 downregulation increases cofilin-1 activity, promoting more migratory and invasive behavior." (PMID 40723199, 2025). "For example, phosphorylated cofilin 1 (p-CFL1) is highly expressed in cisplatin-resistant ovarian cancer 317 cell line p-CFL1 and taxol-resistant ovarian cancer cells." (PMID 35498135, 2022). "In this study, results indicate that high expression of Cofilin-1 in patient sample tissues correlates with decreasing stage of ovarian cancer." (PMID 31700829, 2019). "The re-expression of miR-145 reduces cofilin-1 levels, promotes actin filament stability, and inhibits the formation of metastatic protrusions, underscoring its promise as a therapeutic strategy in ovarian cancer." (PMID 40723199, 2025). "Literature review found Cofilin 1 (CFL1), Ezrin (EZR), Cyclophilin-A (CYPA), Profilin 1 (PFN1), Napsin A (NAPSA) have been found to be associated with the development and progression of OC15–19, and are potential TAAs for ovarian cancer." (PMID 38684875, 2024). "This study investigated the expression levels of AXL, GAS6, Claudin-1, and Cofilin-1, as genes involved in EMT in relation to clinicopathologic features in ovarian cancer patients." (PMID 31700829, 2019).
Parkinson disease (5 papers, 2017 to 2025). A progressive degenerative disorder of the central nervous system characterized by loss of dopamine producing neurons in the substantia nigra and the presence of Lewy bodies in the substantia nigra and locus coeruleus. "We discuss the relevance of αSyn-actin interaction for synaptic function and highlight the actin-depolymerizing protein cofilin-1 as a key player on αSyn-induced actin dysfunction in Parkinson’s disease." (PMID 32903460, 2020). "Comparable to our results after elevated IOP stress, downregulated protein levels of cofilin 1 have also been described after stimulation of microglia using nitrated α-synuclein in a Parkinson’s disease model." (PMID 28740252, 2017). "In contrast, the Amyg showed upregulation of genes linked to oxidative phosphorylation (Atp6v1e1, Atp5mc2, Atp6v0e2), Parkinson disease (Snca, Calm1, Slc39a10), and regulation of actin cytoskeleton (Arpc3, Nckap1, Cfl1), indicating increased mitochondrial metabolism and structural plasticity." (PMID 41394722, 2025).
autoimmune disease (4 papers, 2012 to 2024). A disorder resulting from loss of function or tissue destruction of an organ or multiple organs, arising from humoral or cellular immune responses of the individual to their own tissue constituents. "It is reported that decreased Cfl1 expression is important for early mouse embryo development, and Cotl1 is associated with autoimmune disorders." (PMID 23134655, 2012). "Although the CFL1 and MSN each showed one co-occurrence in our analysis, the peer studies demonstrate they are associated with the pathological mechanisms in autoimmune diseases." (PMID 39767148, 2024). "Autoantibodies directed against cofilin-1 have been found in patients suffering from autoimmune diseases such as rheumatoid arthritis, systemic lupus erythematosus, polymyositis, dermatomyositis, and Behçet's disease." (PMID 28404907, 2017). "In addition to their conventional roles inside of cells, ENO-1 and cofilin-1 can be found on cell surfaces and are also involved in autoimmune diseases." (PMID 38618493, 2023).
colorectal cancer (4 papers, 2015 to 2025). A primary or metastatic malignant neoplasm that affects the colon or rectum. "In line with this, cofilin-1 silencing reduces colorectal cancer cell migration and invasion rates, as well as MMP2 activity." (PMID 34066419, 2021).
COVID-19 (4 papers, 2021 to 2024). A disease caused by infection with severe acute respiratory syndrome coronavirus 2. "Similarly, we found significantly reduced levels of proteins of the actin cytoskeleton network amongst COVID-19 convalescents, e.g. PFN1 and CFL1 (cluster A), partially contrasting what had been found for the acute phase." (PMID 38396092, 2024).
glomerular diseases (4 papers, 2010 to 2018). "Regulation of CFL1 activity plays an important role in glomerular diseases because podocyte specific KO of CFL1 causes sustained proteinuria by 3 months of age and FP effacement by 8 months of age21." (PMID 30115939, 2018). "Taken together these data suggest that pathways that regulate CFL1 activity are likely to play important roles in glomerular disease processes." (PMID 30115939, 2018). "In contrast, when the podocytes undergo foot process effacement because of nephritic glomerular diseases, cofilin-1 was found phosphorylated (inactivated) and translocated to the nucleus of podocytes." (PMID 22190940, 2012). "The expression of phosphorylated cofilin-1 in glomerular diseases suggests a reduced capacity of podocytes to adapt to glomerular pressure differences." (PMID 22190940, 2012). "Moreover, phosphorylation of CFL1 in podocytes is enhanced in human glomerular diseases and is localized to the nucleus." (PMID 30115939, 2018). "In addition, CFL1 phosphorylation (indicating CFL1 inactivation) was observed in human glomerular disease samples and resembled cellular phenotypes of Coro2b knockout cell." (PMID 29162887, 2017). "However, in glomerular diseases that affect podocytes, cofilin-1 was inactivated by phosphorylation and observed in the nucleus." (PMID 20838616, 2010). "Thus, we hypothesize that the expression of phosphorylated cofilin-1 in glomerular diseases suggests a reduced capacity of podocytes to adapt to glomerular pressure differences." (PMID 20838616, 2010).